ZNF623 (zinc finger protein 623)
Description:
May be involved in transcriptional regulation.
Synonyms: KIAA0628
Tractability: PROTAC: UniProt records ubiquitination sites on it; ubiquitination databases record sites on it.
Gene: Protein-coding gene on chromosome 8 (143,635,518 to 143,656,418, forward strand). Ensembl gene ENSG00000183309.
Subcellular location: Nucleus
Subcellular location (Human Protein Atlas): Nucleoplasm
Gene Ontology:
Molecular function: protein binding; DNA-binding transcription factor activity, RNA polymerase II-specific; RNA polymerase II cis-regulatory region sequence-specific DNA binding
Biological process: regulation of transcription by RNA polymerase II
Cellular component: nucleus; nucleoplasm
Genetic constraint (gnomAD): Loss-of-function variants: 16 observed, 25.33 expected, observed/expected ratio (o/e) 0.63, 90% interval 0.43 to 0.96. The upper end of that interval is the gene's LOEUF score, 0.96, which puts it in group 4 of 6, group 1 being the genes least tolerant of losing a copy. Missense variants: 566 observed, 638.48 expected, observed/expected ratio (o/e) 0.89, 90% interval 0.83 to 0.95. Synonymous variants: 224 observed, 232.55 expected, observed/expected ratio (o/e) 0.96, 90% interval 0.86 to 1.08.
Homologues: Orthologues: macaque ZNF623 (97% identical), dog ZNF623 (85% identical), mouse Zfp623 (82% identical), rabbit ZNF623 (81% identical), rat Zfp623 (80% identical), pig ZNF623 (70% identical), guinea pig ZNF623 (70% identical). Paralogues in human: ZNF7 (50% identical), ZNF33B (48% identical), ZNF585B (48% identical), ZNF658 (48% identical), ZNF484 (48% identical), ZNF41 (48% identical), ZNF595 (48% identical), ZNF568 (47% identical), ZNF189 (47% identical), ZNF30 (47% identical), ZNF546 (47% identical), ZNF16 (47% identical), and 164 more.
Diseases named in the same sentence as ZNF623 in open-access papers:
ZNF623 is named in the same sentence as 3 diseases in open-access papers, as found by Europe PMC text mining. Sharing a sentence is not in itself a finding about the gene and the disease. The quoted sentences say what the papers report.
cancer (1 paper, 2022). A tumor composed of atypical neoplastic, often pleomorphic cells that invade other tissues. "Furthermore, three of the CanCord34 genes, namely MROH6, ZNF623, and CCDC166, have no prior PubMed publications in the context of cancer." (PMID 36497066, 2022).
ZNF623 also shares sentences with these, for which no sentence is quoted: tumor (2 papers); breast carcinoma (1).